PRPH2 (peripherin 2)
Description:
Essential for retina photoreceptor outer segment disk morphogenesis, may also play a role with ROM1 in the maintenance of outer segment disk structure (By similarity). Required for the maintenance of retinal outer nuclear layer thickness (By similarity). Required for the correct development and organization of the photoreceptor inner segment (By similarity).
Synonyms: RDS; TSPAN22; rd2; CACD2; AOFMD; AVMD; DS; MDBS1; RP7
Tractability: Antibody: UniProt predicts a signal peptide or a membrane-spanning region; its Gene Ontology location is reachable by antibodies, with medium confidence.
Gene: Protein-coding gene on chromosome 6 (42,696,598 to 42,722,597, reverse strand). Ensembl gene ENSG00000112619.
Subcellular location: Membrane; Cell projection, cilium, photoreceptor outer segment; Photoreceptor inner segment
Gene Ontology:
Molecular function: protein binding; protein homodimerization activity
Biological process: protein localization to plasma membrane; protein maturation; visual perception; response to low light intensity stimulus
Cellular component: membrane; photoreceptor inner segment; plasma membrane; photoreceptor outer segment
Genetic constraint (gnomAD): Loss-of-function variants: 17 observed, 32.98 expected, observed/expected ratio (o/e) 0.52, 90% interval 0.35 to 0.77. The upper end of that interval is the gene's LOEUF score, 0.77, which puts it in group 3 of 6, group 1 being the genes least tolerant of losing a copy. Missense variants: 430 observed, 464.38 expected, observed/expected ratio (o/e) 0.93, 90% interval 0.86 to 1. Synonymous variants: 165 observed, 195.21 expected, observed/expected ratio (o/e) 0.85, 90% interval 0.74 to 0.96.
Gene-disease validity (ClinGen):
ClinGen rates the evidence that PRPH2 causes each of these diseases.
PRPH2-related retinopathy (semidominant): Definitive. Any retinopathy caused by a variant or variants in the PRPH2 gene.
Homologues: Orthologues: chimpanzee PRPH2 (99% identical), macaque PRPH2 (99% identical), dog PRPH2 (92% identical), pig PRPH2 (91% identical), mouse Prph2 (91% identical), rabbit PRPH2 (91% identical), rat Prph2 (91% identical), guinea pig PRPH2 (87% identical), tropical clawed frog tbcc (69% identical), zebrafish prph2a (64% identical), zebrafish prph2b (61% identical). Paralogues in human: ROM1 (34% identical), CD37 (15% identical), TSPAN14 (15% identical), TSPAN15 (14% identical), TSPAN17 (14% identical), CD151 (14% identical), TSPAN11 (14% identical), CD82 (14% identical), TSPAN5 (14% identical), TSPAN7 (14% identical), CD53 (13% identical), TSPAN6 (13% identical), and 20 more.
Diseases named in the same sentence as PRPH2 in open-access papers:
PRPH2 is named in the same sentence as 66 diseases in open-access papers, as found by Europe PMC text mining. Sharing a sentence is not in itself a finding about the gene and the disease. The quoted sentences say what the papers report.
retinal degeneration (35 papers, 2008 to 2026). Degeneration of the retina. "PRPH2, essential for OS disc morphogenesis and structural maintenance, causes severe OS disorganization and retinal degeneration when mutated." (PMID 41805095, 2026). "The rd2 mouse model, characterized by a mutation in the Prph2 gene, exhibits abnormal development of photoreceptor outer segments, resulting in progressive retinal degeneration." (PMID 40170065, 2025). "Taken together, these results signify the therapeutic efficacy of reducing levels of RHO as a strategy in impeding retinal degeneration caused by PRPH2 pathogenic variants." (PMID 38834544, 2024). "Central areolar choroidal dystrophy is an inherited disorder characterized by progressive choriocapillaris atrophy and retinal degeneration and is usually associated with mutations in the PRPH2 gene." (PMID 37914688, 2023). "The rd2 retinal degeneration model has a spontaneous dominant mutation in the peripherin 2 protein (Prph2)." (PMID 31717957, 2019). "Mutations in the corresponding PRPH2 gene disrupt OS architecture and are the cause of blinding hereditary retinal degeneration." (PMID 28723922, 2017). "Mutations in the photoreceptor protein peripherin-2 (also known as RDS) cause severe retinal degeneration." (PMID 26406599, 2015). "The ‘retinal degeneration slow’ (rds) mouse (Rd2) is the classical model for retinal degeneration and carries a Prph2 mutation." (PMID 25650393, 2015). "Our findings underscore PE as a tool for generating the PRPH2 c.828+1G>A variant, thereby facilitating future genotype-phenotype studies that will also inform us about the mechanisms of retinal degeneration for the other PRPH2 c.828 splice site mutations that activate the same cryptic splice site." (PMID 41210588, 2025). "PRPH2-deficient (rds/rds) mice fail to develop OSs and undergo subsequent retinal degeneration." (PMID 35698136, 2022). "Interestingly, variants in rhodopsin, Pde6a, Pde6b, Prph2 and Rom1 are associated with inherited retinal degeneration in both humans and mice, and their downregulation may underlie the retinal degenerative phenotype observed in Hbs1ltm1a/tm1a mice." (PMID 38966981, 2024). "PRPH2-mediated retinal degenerations represent a substantial burden for patients, ultimately resulting in progressive blindness." (PMID 41210588, 2025). "Murine models with an increased RHO/PRPH2 ratio exhibited formation of discs with significantly larger diameters than wild type, accelerated retinal degeneration, and decreased physiological function." (PMID 38834544, 2024). "Phenotypic variability in PRPH2-related retinal degeneration is attributed to the presence of other genetic modifiers." (PMID 39610584, 2024). "Mutations in the photoreceptor-specific tetraspanin gene peripherin-2 (PRPH2) lead to widely varying forms of retinal degeneration ranging from retinitis pigmentosa to macular dystrophy." (PMID 37466729, 2023). "Slow, progressive rate of degeneration reflective of PRPH2 retinitis pigmentosa in humans, useful for optogenetic therapy safety and efficacy assessments in early stage retinal degeneration." (PMID 33262683, 2020). "The second known targeting sequence resides within the C-terminus of peripherin/retinal degeneration slow (also known as rds or peripherin-2, hereafter referred to as peripherin)." (PMID 23342122, 2013). "More recently, CK30-PEG nanoparticles were used to deliver a DNA plasmid which expressed the gene peripherin 2 (Prph2) to the retina of Prph2+/- mice, which have a phenotype of slow retinal degeneration." (PMID 20932321, 2010). "SRT injection of CK30-PEG-Prph2 nanoparticles significantly reduced retinal degeneration in Prph2+/- mice, and sustained elevated Prph2 gene expression for up to 4 months." (PMID 20932321, 2010). "A study of knockout and transgenic mice showed that retinal degeneration occurs when the combined level of both Rom1 and Prph2 is only about 60% of their combined level in wild-type mice." (PMID 20300562, 2010).
retinal degeneration (continued). "PRPH2/RDS is mainly located in the outer segment of both rod and cone, and defects in this gene are associated with retinal degenerations." (PMID 20419148, 2010). "Early work exploring the mechanisms of PRPH2-associated disease using the Prph2+/− model demonstrated that the PRPH2 level is critical for maintaining photoreceptor health and that PRPH2 haploinsufficiency leads to retinal degeneration, first targeting rods and later cones." (PMID 37466729, 2023). "An AAV vector was first reported to be successful for the treatment of a preclinical model of IRD in 1998, when it was used to restore visual function in the retinal degeneration slow (rds) mouse through the reintroduction of a wild-type copy of the PRPH2 gene." (PMID 34768969, 2021). "By contrast, there has been no clear evidence thus far that mutations in retinal outer segment membrane protein 1 (ROM1) alone cause retinal degeneration, although it is well known that only persons who are double heterozygous for ROM1 and PRPH2 develop RP in a digenic inheritance pattern." (PMID 20300562, 2010). "Peripherin-2, a protein crucial for photoreceptor ciliary function, follows an ESCRT-0 mediated route for correct ciliary targeting and mutations perturbing this interaction could be causative for retinal degeneration." (PMID 36776558, 2023). "Here, we utilize two different models of inherited retinal degeneration, the rhodopsin P23H knockin (RhoP23H/+) model of RP and the Prph2 Y141C knockin (Prph2Y141C/+) model of cone-rod dystrophy to evaluate whether eliminating retbindin has broad effects on retinal degeneration." (PMID 33138244, 2020). "Moreover, this is the first study in which the onset and progression of PRPH2-associated retinal degeneration have been characterized over time by different techniques, and this is also the first time that synaptic remodeling of the OPL has been described in a model of IRD associated with rds/Prph2." (PMID 37914688, 2023).
retinitis pigmentosa (33 papers, 2012 to 2025). Retinitis pigmentosa (RP) is an inherited retinal dystrophy leading to progressive loss of the photoreceptors and retinal pigment epithelium and resulting in blindness usually after several decades. "We previously reported on a 67-year-old patient with retinitis pigmentosa (RP) caused by a rare heterozygous PRPH2 c.828+1G>A splice site mutation." (PMID 41210588, 2025). "These Prph2 heterozygous mice were chosen for their clinical relevance, as PRPH2-associated retinitis pigmentosa typically exhibits autosomal dominant inheritance." (PMID 38834544, 2024). "The PRPH2 mutation c.582-1G>A is a rare variant reported in retinitis pigmentosa and pattern dystrophy." (PMID 39298723, 2023). "Around 200 mutations of PRPH2 are shown to cause a heterogeneous set of inherited retinal diseases, including retinitis pigmentosa, cone-rod dystrophy, and macular dystrophies." (PMID 37991486, 2023). "In 19 families, where the disease segregated with the dominant PRPH2 c.828+3A>T variant, the phenotypes were very discordant, ranging from mild pattern dystrophy to severe cone-rod dystrophy, retinitis pigmentosa and central areolar chorioretinal dystrophy." (PMID 35353811, 2022). "Other diseases that are based on instability of the photoreceptors, e.g., due to gene mutations in the peripherin-2 (PRPH-2) gene such as retinitis pigmentosa, can also lead to the formation of choroidal neovascularizations." (PMID 35327496, 2022). "Pheripherin2 is a structural protein of the photoreceptor outer segment disc, and over 80 PRPH2 pathological mutations have been linked to RD, with clinical presentations ranging from retinitis pigmentosa to various forms of macular degeneration." (PMID 32313077, 2020). "According to the Human Gene Mutation Database, there are over 190 mutations in the peripherin-2 gene, PRPH2, that cause a heterogeneous set of retinal dystrophies, including retinitis pigmentosa, pattern dystrophy and macular dystrophy." (PMID 32410962, 2020). "Mutations in the peripherin 2 gene are associated with many human retinal degenerative diseases, like retinitis pigmentosa and adult vitelliform macular dystrophy." (PMID 25629227, 2015). "This gene has been linked to several other retinopathies including pattern macular dystrophy and retinitis pigmentosa, and it has been previously suggested that mutations in PRPH2 can mimic the STGD phenotype or modify disease severity." (PMID 22863181, 2012). "Previously associated with retinitis pigmentosa and pattern dystrophies, PRPH2 may contribute to AMD susceptibility through mechanisms affecting photoreceptor stability and function." (PMID 41136342, 2025). "PRPH2-associated diseases are largely autosomal dominant, though digenic forms exist, and clinical manifestations of PRPH2 mutations can vary widely from retinitis pigmentosa to macular dystrophy." (PMID 37466729, 2023). "In contrast, mutations in PRPH2 are known to cause a variety of retinal phenotypes and have been described in subjects with autosomal dominant adRP, cone dystrophy, macular dystrophy, and digenic retinitis pigmentosa." (PMID 29053642, 2017). "Peripherin 2 is known to be selectively expressed in the photoreceptor outer segment of the retina, and mutations in the peripherin 2 gene are commonly associated with retinal degenerative diseases, like retinitis pigmentosa and autosomal dominant macular dystrophy in man." (PMID 25629227, 2015). "Vessel density was found to be highest in EFEMP1, BEST1, TIMP3, RS1, and PRPH2 (11.0%, 10.4%, 10.1%, 10.1%, 9.2%) and was lower in retinitis pigmentosa (RP) and Leber congenital amaurosis genes." (PMID 39896422, 2025). "Pathogenic mutations in PRPH2 can lead to a wide spectrum of IRD presentations, including retinitis pigmentosa (RP), cone/cone–rod dystrophy (CD/CRD), and macular dystrophy (MD), as previously reported." (PMID 38474159, 2024).
retinitis pigmentosa (continued). "The diagnosis of early-onset retinitis pigmentosa in this patient was even earlier than observed in the PRPH2-related patients with RP of our cohort, which seems to be a compatible phenotype with IMPG2 causative variants." (PMID 38474159, 2024). "Peripherin2/RDS-associated disease (PRPH2/RDS) is generally associated with an autosomal-dominant inheritance and is known to cause retinitis pigmentosa (RP), several forms of macular dystrophy, and cone-rod dystrophies." (PMID 37569703, 2023). "The phenotypes tested include Prph2+/Δ307, Prph2rd2/rd2, Rho–/–, PDE6βrd1/rd1, Crb1rd8/rd8, and Gnat1–/–, the first four being models of retinitis pigmentosa, the following, a model of LCA, and the latter a model of stationary night blindness." (PMID 32923439, 2020). "Two of these mutations, Y141C and C213Y, are of particular interest because, in patients, they are largely characterized by pattern dystrophy (although some Y141C patients present with retinitis pigmentosa), yet they have opposing effects on PRPH2 complex assembly." (PMID 37466729, 2023). "Individuals affected by PRPH2 mutation are known to have pattern dystrophy (butterfly-shaped pigment dystrophy and Adult-onset foveomacular vitelliform dystrophy) with a broad spectrum of clinical appearance, LCA and retinitis pigmentosa." (PMID 33957996, 2021). "We assessed gliosis across a number of clinically relevant murine models of inherited retinal disease that represent a range of degeneration rates: three models of retinitis pigmentosa (RP) (Prph2+/Δ307, Rho-/-, Pde6brd1/rd1) and a model of Leber Congenital Amaurosis (LCA) (Crb1rd8/rd8)." (PMID 25793273, 2015). "In Prph2 “null” Rds mice, the lack of peripherin downregulates rhodopsin gene expression, causing a gradual loss of rod cells characteristic of macular diseases as retinitis pigmentosa." (PMID 35656327, 2022). "Mutations in PRPH2 (also known as TSPAN22 or RDS) and in ROM1 (also known as TSPAN23), which function together in stabilising the structure of photoreceptor outer segment discs, can cause retinitis pigmentosa, while mutations in TSPAN12 can cause familial exudative vitreo-retinopathy type 5 (EVR5)." (PMID 31073882, 2019). "Yet, mutations in ROM1 typically cause digenic retinitis pigmentosa in conjunction with mutations in PRPH2, except for a handful of reports of mutations in ROM1 in patients without accompanying PRPH2 mutations." (PMID 37991486, 2023).
Macular dystrophy (29 papers, 2017 to 2025). Macular dystrophy is a nonspecific term for retinal degeneration, generally confined to the macula, usually presumed of genetic origin. "The missense variant c.653C>G (p.Ser218Trp), located on the exon 2 of PRPH2, was found at the heterozygous state in a single patient (pt-1A) diagnosed with macular dystrophy, with ERG showing a reduced photopic response suggestive of cone dysfunction." (PMID 40722607, 2025). "More than 200 PRPH2 variants have been reported to be involved in the onset of RP, macular dystrophies, or central areolar choroidal dystrophy, displaying extensive phenotypic heterogeneity." (PMID 40722607, 2025). "PRPH2 variants are associated with a range of disease phenotypes including macular dystrophy, RP, and Leber congenital amaurosis." (PMID 38219857, 2024). "The patient PRPH2-018-5, who carried the variant p.Arg142Trp, presented with macular dystrophy with different severities between both eyes on funduscopy and OCT." (PMID 38474159, 2024). "With regard to PRPH2, phenotypes can vary widely, so we restricted our analysis to missense changes at two codons (142 and 172), which more frequently cause macular dystrophy in our cohort." (PMID 38700873, 2024). "Whereas many PRPH2 mutations cause macular dystrophy, our updated understanding of disease mechanisms from this and previous studies suggests that macular disease likely arises after abnormalities in outer segment structure." (PMID 37466729, 2023). "There is a vast variety of PRPH2 mutations associated with autosomal dominant retinal degenerative diseases, including RP, several forms of macular dystrophy and cone rod dystrophies." (PMID 32213850, 2020). "Genetic screening for genes associated with macular dystrophies, especially PRPH2, can be beneficial to help identify AMD‐mimicking dystrophies." (PMID 30215852, 2018). "Similarly, the c.629C > G, p.Pro210Arg variant in the PRPH2 gene with AD forms of macular dystrophy and RP." (PMID 38956727, 2024). "Case 1b is a PRPH2-associated macular dystrophy mimicking Stargardt disease." (PMID 38066771, 2023). "We found that eliminating Rtbdn in the R172W Prph2 model of macular dystrophy exacerbated Prph2-associated retinal disease, suggesting RTBDN may play a protective role in IRD." (PMID 33138244, 2020). "Based on our national registry, BEST1-related diseases accounted for 0.21% of IRD patients, 6.8% of macular dystrophy patients, and 40.9% of bestrophinopathy patients (with PRPH2 representing 7.1% of these patients)." (PMID 40891781, 2025). "We searched the electronic patient records of our large inherited retinal disease cohort, quantifying numbers of males and females with the more common (non-ABCA4) inherited macular dystrophies (associated with BEST1, EFEMP1, PROM1, PRPH2, RP1L1, and TIMP3)." (PMID 38700873, 2024). "Heterozygous individuals in ABCA4 disease and control cohort harboring variants with MAF<0.005 and CADD score >25, in each macular dystrophy gene CDHR1, CHM, CRX, ELOVL4, PROM1, PRPH2, and ROM1." (PMID 35353811, 2022). "Heterozygous individuals in ABCA4 disease and control cohort harboring rare variants in macular dystrophy genes CDHR1, CHM, CRX, ELOVL4, PROM1, PRPH2, ROM1." (PMID 35353811, 2022). "Based on the actual minor allele frequencies, the PRPH2 variants c.910C (p.Gln304) and c.1013A (p.Asp338) are the most common variants in the STGD1-like macular dystrophy genes at MAF~0.2 each in the European population." (PMID 35353811, 2022). "Panel-based NGS was performed to identify potentially disease-causing genetic variants in previously identified retinal or macular dystrophy genes, including the five known STGD genes (ABCA4, PROM1, PRPH2, VMD2, and ELOVL4)." (PMID 33988224, 2021). "Previously, we found that elimination of Rtbdn accelerated degeneration in the Prph2 R172W model of macular dystrophy." (PMID 33138244, 2020).